IDH1 (isocitrate dehydrogenase (NADP(+)) 1)
Diseases named in the same sentence as IDH1 in open-access papers (continued):
Sharing a sentence is not in itself a finding about the gene and the disease.
chondrosarcoma (continued). "Since mutations in IDH1 were shown to cause global hypermethylation in tumors, we assessed the methylome in the chondrosarcoma cell lines." (PMID 25895133, 2015). "Genome-wide CpG methylation sequencing of chondrosarcoma biopsies revealed that IDH1/2 mutations are associated with DNA hypermethylation at CpG islands but not at other genomic regions." (PMID 25895133, 2015). "The study shows that if an IDH1 mutation were detected in a primary central chondrosarcoma, it is always detected at the time of presentation, and the same mutation is detected in local recurrences and metastatic events." (PMID 25432631, 2015). "Central conventional chondrosarcomas carry mutations in IDH1/2 in 38-70% of primary central chondrosarcomas (arising without a preexisting benign enchondroma) and in 86% of the secondary central chondrosarcomas." (PMID 25895133, 2015). "Compared to IDH1/2 wildtype cell lines, chondrosarcoma cell lines harboring an endogenous IDH1 (n=3) or IDH2 mutation (n=2) showed up to a 100-fold increase in intracellular and extracellular D-2-HG levels." (PMID 25895133, 2015). "We here use a unique panel of chondrosarcoma cell lines harboring endogenous IDH1/2 mutations that were retained during culturing." (PMID 25895133, 2015). "In chondrosarcoma and intrahepatic cholangiocarcinoma, the R132C alteration in IDH1 is the most frequent mutation, while in angioimmunoblastic T-cell lymphoma mutations in IDH2 are predominant." (PMID 24529257, 2014). "The IDH1 R132H mutation found in osteosarcoma sample 3-1 is a frequent event in low-grade brain tumors, central and periosteal chondromas, and central chondrosarcomas." (PMID 25300797, 2014). "This is puzzling as the driver mutation in human central chondrosarcoma is IDH1 or IDH2, while in peripheral chondrosarcomas this is not known, but no indication for involvement of Fos is found." (PMID 23880362, 2013). "We here present three chondrosarcoma cell lines, one carrying an IDH1 R132C mutation, one carrying an IDH2 R172W mutation, and one wild type for IDH mutations with stable karyotypes and steady growth patterns." (PMID 22928481, 2012). "Together, these data suggest that in chondrosarcoma tumor models, expression of IDH1 R132 mutants is associated with increased hypermethylation compared to WT, while IDH1 R132Q expression is associated with increased regions of hypomethylation compared to R132H." (PMID 40188944, 2025). "Pathology demonstrates a grade 3 chondrosarcoma with IDH1 R132G mutation identified." (PMID 41138165, 2025). "However, a recent study found that it has an R132C mutation in IDH1, which is commonly associated with chondrosarcomas cell lines." (PMID 40075728, 2025). "However, it was recently found to have an R132C mutation in IDH1, which is a characteristic commonly associated with chondrosarcomas." (PMID 40075728, 2025). "SPEDOX-6 remarkably suppresses HT-1080 (fibrosarcoma cell line STS model but recently reclassified as dedifferentiated chondrosarcoma due to characteristic IDH1 mutation, with the lowest FcRn expression level among cancer cell lines), with 3 out of 10 mice attaining tumor-free status." (PMID 40075728, 2025). "Nevertheless, the detection rate of the IDH1 mutation was almost similar for all three methods in the whole sample of 96 tumors (36%, 36%, and 37%), but in chondrosarcomas, qPCR-DMA-Sanger showed a slightly lower sensitivity (46%) compared to biochip (48.3%) or IHC (48.2%) methods." (PMID 38248076, 2024). "IDH1/2 mutations accounted for 13 of 15 high-grade chondrosarcomas." (PMID 38170705, 2024). "Moreover, the loss of mutant IDH1 resulted in decreased chondrosarcoma tumor formation and D-2HG production in a xenograft model." (PMID 39684713, 2024).
chondrosarcoma (continued). "Interestingly, 40% of chondrosarcomas that harbor an IDH1 R132C mutation are characterized by a high production of 2-HG." (PMID 39123479, 2024). "Recently, IDH1/2 mutations were found in the tumor tissue of benign cartilage tumors and in conventional chondrosarcoma and highly aggressive dedifferentiated chondrosarcomas; however, their association with prognosis remains controversial, such as their use in patient treatment." (PMID 38170705, 2024). "The hot-spot IDH1/2 mutations have been found to be hallmarks of several types of chondroid tumors and are mainly encountered in benign enchondromas (up to 87%), central conventional chondrosarcomas (about 50%), and dedifferentiated chondrosarcomas." (PMID 38248076, 2024). "Therefore, it was not possible to attribute the current pathology to the original chondrosarcoma on the basis of the IDH1 or IDH2 mutation." (PMID 37171609, 2023). "In addition, mutations found in chondrosarcoma such as mutations located in IDH1/2 (>50% of chondrosarcomas) have been described to induce constitutive activation of HIF-1α and Hif-2α factors." (PMID 37046623, 2023). "Due to the resistance of chondrosarcomas to conventional chemotherapy and radiotherapy, the IDH1/2 mutations could represent a viable option for Bcl-2 inhibitors." (PMID 37720343, 2023). "Given the apparent association of HIF-1α expression with IDH1 mutation, we asked whether such mutation confers angiogenic properties on the chondrosarcoma JJ012 cells." (PMID 35198082, 2022). "We found IDH1 R132C somatic mutation in chondrosarcoma lesions in the present case." (PMID 35765075, 2022). "In addition, approximately half of chondrosarcoma cases carry an IDH1 or IDH2 mutation, and therefore mutational testing can be helpful to verify the diagnosis and to exclude chondroblastic osteosarcoma." (PMID 35875137, 2022). "Thus, the HIF pathway represents a promising candidate for combinatorial regimens to target IDH1 mutated chondrosarcomas." (PMID 35198082, 2022). "DS-1001b impairs the proliferation of chondrosarcoma cells with IDH1 mutations in vitro and vivo." (PMID 36091829, 2022). "A comparative study found that compared with low-grade chondrosarcoma, the expression of glycolysis-related genes is increased, and glutaminase is also high in high-chondrosarcoma, but glutamine degradation has nothing to do with IDH1/2 mutation." (PMID 33981605, 2021). "IDH1/2 mutations are prevalent in cartilaginous tumors including chondrosarcoma." (PMID 34085407, 2021). "IDH1/2 mutations were prevalent in some specific types of chondrosarcoma and assessment of these mutations in challenging cases could help distinguish from chordoma or osteosarcoma." (PMID 34085407, 2021). "However, published data are equivocal regarding the association of IDH1/2 mutations and outcomes of chondrosarcoma patients." (PMID 34085407, 2021). "The impact of IDH1/2 mutations on chondrosarcoma patient survival is unclear." (PMID 34085407, 2021). "The most common genetic alteration in central conventional chondrosarcoma is the hotspot mutation affecting the arginine residues encoded by the isocitrate dehydrogenase 1 and -2 (IDH1 or IDH2, collectively referred to as IDH) genes (R132 and R140/R172, respectively), occurring in ~50% of the cases." (PMID 33266275, 2020). "Molecular analysis of conventional chondrosarcoma components revealed an IDH1 c.395G>T, p.(Arg132Leu) mutation in two cases, and an IDH1 c.394C>T, p.(Arg132Cys) mutation in one case, with identical IDH mutations in the clear cell chondrosarcoma counterpart (100%)." (PMID 31297850, 2019). "It has been suggested that IDH1/2 mutated tumours depend on glutaminolysis for their α-KG supply, which led to two clinical trials that were recently started in IDH1/2 mutated solid tumours, including chondrosarcomas." (PMID 29576625, 2018). "This led us to investigate the function of the IDH1/2 mutation in chondrosarcoma." (PMID 25895133, 2015).
chondrosarcoma (continued). "To evaluate the functional role of IDH1/2 mutations we used a chondrosarcoma cell line panel including five IDH1/2 wildtype, three endogenous IDH1 mutant and two endogenous IDH2 mutant cell lines, originating from conventional central as well as dedifferentiated chondrosarcomas." (PMID 25895133, 2015). "Interestingly, only CpG islands probes show hypermethylation in the chondrosarcoma cell lines with an IDH1/2 mutation, whereas the shores and shelves show hypermethylation in the IDH1/2 wildtype cell lines." (PMID 25895133, 2015). "In addition, we now show that when an IDH1 mutation is present in a solitary primary central conventional chondrosarcoma, the same mutation is always detected in local recurrences and metastatic events." (PMID 25432631, 2015). "~54% of the dedifferentiated chondrosarcomas contain mutations in IDH1 or IDH2." (PMID 25895133, 2015). "We conclude that IDH1 mutations represent a recurrent genetic event in solitary central chondrosarcomas, that they occur early in disease development and persist during tumour recurrence and metastatic disease thereby adding to the existing evidence that such mutations represent drivers of disease." (PMID 25432631, 2015). "While mutations in IDH1/2 are early events in benign cartilage tumors, we evaluated whether these mutations play a role in malignant chondrosarcomas." (PMID 25895133, 2015). "A very recent review suggested that chondrosarcoma patients might benefit from antiangiogenic therapy and that tumors harboring isocitrate dehydrogenase 1 (IDH1)-mutations might benefit from treatment with IDH1-inhibitors." (PMID 36158667, 2022). "Majority of chondrosarcomas are associated with a number of genetic alterations, including somatic mutations in isocitrate dehydrogenase 1 (IDH1) and IDH2 genes, but the downstream effects of these mutated enzymes on cellular metabolism and tumor energetics are unknown." (PMID 33762012, 2021). "Inhibitors of mutated IDH1/2 enzymes entered clinical trials for targeted therapy of gliomas and may represent an interesting opportunity also for patients with chondrosarcomas." (PMID 32295254, 2020). "Metabolomic analysis of xenograft tissue supported a possible role of lipid oxidation being downregulated in IDH1 R132Q versus R132H in our chondrosarcoma models." (PMID 40188944, 2025). "This included decreased COL9A2 transcripts upon expression of IDH1 R132Q versus WT, a type IX collagen often downregulated in high-grade versus low-grade chondrosarcomas." (PMID 40188944, 2025). "The efficacy of IDH1 inhibitors in chondrosarcoma are currently being assessed in clinical trials, though populations are heterogeneous or limited to only patients with conventional chondrosarcoma." (PMID 40364090, 2025). "Driver mutations in IDH1 and IDH2 are initiating events in the evolution of chondrosarcoma and several other cancer types." (PMID 41299743, 2025). "In general, both IDH1 R132H and R132Q chondrosarcoma tumor models showed the same hypermethylation localization trends compared to WT, with promoter and intronic regions showing the most hypermethylation." (PMID 40188944, 2025). "We found here that alterations in the Wnt pathway represented another persistent phenotype in our xenograft models, with primarily hypermethylation (and some hypomethylation) of gene pathway members upon expression of IDH1 R132Q in chondrosarcoma models." (PMID 40188944, 2025). "Here, we present evidence that mutant IDH1 is recurrently lost in metastatic central chondrosarcoma." (PMID 41299743, 2025). "There is a clear need for new treatment options for metastatic chondrosarcoma, as patients rarely survive beyond two years and recent trials of IDH1 inhibitors report variable responses." (PMID 41299743, 2025).
chondrosarcoma (continued). "Recent studies have suggested several promising biomarkers and therapeutic targets for chondrosarcoma, including isocitrate dehydrogenase (IDH1/2) and COL2A1." (PMID 38541003, 2024). "IDH1 and IDH2 mutations play a significant role in the progression and molecular characteristics of chondrosarcomas, as identified in recent multi-omics studies." (PMID 39590345, 2024). "IDH1 and IDH2 mutations occur in approximately 50–75% of chondrosarcoma cases, with the prevalence varying by tumor subtype." (PMID 39684713, 2024). "In malignant tumors, IDH1-positive cases were predominantly found in 48% of chondrosarcomas, which is consistent with other studies." (PMID 38248076, 2024). "Mutations in genes such as IDH1 and IDH2, which are involved in cellular metabolism, have been frequently observed in both skeletal and extraskeletal chondrosarcomas." (PMID 39717304, 2024). "In our previous study, we used the CRISPR/Cas9 system to knock out mutant IDH1 in two chondrosarcoma cell lines." (PMID 39684713, 2024). "Using high-throughput screening, we evaluated a panel of anticancer agents in IDH1-mutant chondrosarcoma cell lines and their mutant IDH1 knockout derivatives." (PMID 39684713, 2024). "Ongoing trials are still recruiting chondrosarcoma patients to understand the more appropriate setting for IDH1/2 inhibitors." (PMID 37752419, 2023). "This study aimed to make a prognostic evaluation by immunohistochemistry using the markers IDH1 and Ki67 in patients who underwent treatment for chondrosarcoma." (PMID 37469494, 2023). "To test this differential diagnosis, we examined features common to chondrosarcomas, i.e., an IDH1 or IDH2 mutation described in approximately 38.7% and 12.1% of chondrosarcoma specimens, respectively." (PMID 37171609, 2023). "One of the most common mutations observed in many cases of chondrosarcoma, including DDCS, is mutations in the IDH1 and IDH2 genes." (PMID 37568740, 2023). "Recent studies have suggested several promising biomarkers and therapeutic targets for chondrosarcoma, including IDH1/2, COL2A1, and PD-L1." (PMID 35163019, 2022). "Based on this study, ivosidenib is a promising treatment option for patients with mutant IDH1 chondrosarcoma." (PMID 35163019, 2022). "Recent studies have suggested several promising biomarkers and therapeutic targets for chondrosarcoma, including IDH1/2 and COL2A1." (PMID 35163019, 2022). "We employed the IDH1-mutant chondrosarcoma JJ012 cell line, CRSPR/Cas9 mutant IDH1 (IDH1mut) knockout (KO) JJ012 clones, and their derived xenografts." (PMID 35198082, 2022). "In a phase I study of ivosidenib (NCT02073994), a selective inhibitor of mutant IDH1, 21 patients with mutant IDH1 advanced chondrosarcoma were treated with ivosidenib (100 mg twice daily to 1200 mg once daily)." (PMID 35163019, 2022). "A clinical trial evaluating the treatment of chondrosarcoma with ivosidenib (an oral inhibitor of mutant IDH1) was performed, and its tolerability was confirmed." (PMID 35408900, 2022). "Somatic gain-of-function variants in IDH1 and IDH2 have been described in the enchondromas, vascular anomalies and chondrosarcomas of approximately 80% of the individuals with OD and MS." (PMID 36480544, 2022). "For this we measured IDH1 expression in the chondrosarcoma xenografts derived from parental and IDH1mut KO JJ012 cells that we have previously established." (PMID 35198082, 2022). "IDH1/2 mutations are found in several cancer types, including AML, gliomas, chondrosarcoma and intrahepatic cholangiocarcinoma." (PMID 33879235, 2021). "Pharmacological inhibition of IDH1 reduced colony formation, migration, proliferation, and induced apoptosis in chondrosarcoma cells in vitro." (PMID 34938658, 2021).
chondrosarcoma (continued). "IDH1 and IDH2 are NADP-dependent enzymes that are mutated in 38-70% of conventional and dedifferentiated chondrosarcoma cases and induce a neomorphic enzymatic activity." (PMID 34938658, 2021). "Twelve of the 17 amino acids measured (Val, Met, His, Gly, Pro, Ser, Asn, Ala, Leu/Ile, Phe, Tyr, and Orn) were significantly elevated in mutant IDH1 chondrosarcomas." (PMID 33762012, 2021). "A different and more complex profile was found for the early TCA cycle intermediates—citrate and α-KG trended to increase in mutant IDH1 but decrease in mutant IDH2 chondrosarcomas." (PMID 33762012, 2021). "We then selected the chondrosarcoma cell line SW1353, which harbors an IDH2 mutation (R172S/+), as well as the cholangiocarcinoma cell line RBE, which harbors an IDH1 mutation (R132S/+) for combination ATR and PARP inhibitor studies." (PMID 34027408, 2021). "So far, multi-kinase receptor inhibitors have demonstrated some improvements in osteosarcomas and IDH-1/2 inhibitors in a minority of chondrosarcomas." (PMID 34831119, 2021). "This review focuses on metabolic changes in chondrosarcoma, and the relationship between signaling via isocitrate dehydrogenase 1 and 2 (IDH1 and IDH2), hedgehog, PI3K-mTOR-AKT, and SRC, as well as histone acetylation and angiogenesis." (PMID 34938658, 2021). "As a side note, the benefit of IDH1 inhibitors in patients with chondrosarcoma is controversial, in part due to the different histological subtype with various disease aggressiveness and clinical outcome." (PMID 33879235, 2021). "Mutations in the isocitrate dehydrogenase (IDH1 or IDH2) genes are common in enchondromas and chondrosarcomas, and lead to elevated levels of the oncometabolite D-2-hydroxyglutarate causing widespread changes in the epigenetic landscape of these tumors." (PMID 33266275, 2020). "Robust, persistent plasma 2-HG inhibition was observed in IDH1-mutant cholangiocarcinoma and chondrosarcoma." (PMID 31028664, 2020). "Phase 1B results showed partial response in a patient with IDH-1 mutant chondrosarcoma and remained on study for seven months before discontinuing due to toxicity." (PMID 32707689, 2020). "Overall, our data showed that integrin-mediated cell-ECM interactions contribute to IDH1-mutant chondrosarcoma cell migration and/or cell adhesion." (PMID 31935911, 2020). "Evidently, IDH1/2 and GNAS mutations are examples of useful molecular markers pathognomonic for chondrosarcoma and fibrous dysplasia, respectively." (PMID 31838586, 2020). "In vitro functional assays further demonstrated that integrin-mediated cell-matrix interactions contributed to the tumorigenicity of IDH1-mutant chondrosarcoma cells." (PMID 31935911, 2020). "We further demonstrated that deregulation of integrin-mediated processes contributed to the tumorigenicity of IDH1-mutant chondrosarcoma cells." (PMID 31935911, 2020). "Concurrent IDH1 and IDH2 mutations have been reported in two AMLs,5 four anaplastic gliomas, and three chondrosarcomas." (PMID 32333643, 2020). "In this study, we knocked out mutant IDH1 (IDH1mut) in two chondrosarcoma cell lines using the CRISPR/Cas9 system." (PMID 31935911, 2020). "Proliferation and clonogenic assays were performed in chondrosarcoma cell lines after γ-radiation in combination with mutant IDH1 inhibitor AGI-5198." (PMID 31160965, 2019). "Molecular analysis of the conventional chondrosarcoma component for IDH1 and IDH2 was possible in all cases." (PMID 31297850, 2019). "In support of this possibility, restoration of high NADPH levels by inhibiting the mutant IDH1 isoform in HT1080 chondrosarcoma cells protects them against UVA-mediated NER inhibition." (PMID 27324272, 2016). "Two human chondrosarcoma cell lines, JJ012 and HT1080 with endogenous IDH1 mutations and a human chondrocyte cell line C28 with wild type IDH1 were employed in our study." (PMID 26368816, 2015).